RETN (resistin)
Diseases named in the same sentence as RETN in open-access papers (continued):
Sharing a sentence is not in itself a finding about the gene and the disease.
ischemic stroke (continued). "Our large cross-sectional data set representative of the general Japanese population demonstrated that serum resistin concentrations were greater in subjects with ischemic stroke, especially in those with lacunar and atherothrombotic infarction." (PMID 19922611, 2009). "Resistin levels were also increased in symptomatic patients with ischemic stroke when compared to asymptomatic patients (p < 0.001), and elevated levels of resistin also predicted increased risk of cerebral symptomology (odds ratio 1.237, 95% confidence interval [CI] 1.079–1.420, p = 0.002)." (PMID 37623863, 2023). "The present study showed that the association between circulating resistin and ischemic stroke was independent of hs-CRP and other confounding factors." (PMID 19922611, 2009). "Such a discrepancy between experimental and clinical results may be explained by the role of resistin in atherosclerosis onset and plaque development, one of the major causes of ischemic stroke in humans which is usually not represented in experimental models of ischemic stroke." (PMID 36745280, 2023). "In Model 1, the age- and sex-adjusted ORs for total CVD and ischemic stroke increased with quintile of serum resistin (p for trends, 0.02 for CVD, < 0.001 for ischemic stroke)." (PMID 19922611, 2009). "When CVD was divided into types, subjects with ischemic stroke had greater resistin concentrations than those without CVD (p < 0.001)." (PMID 19922611, 2009). "However, a recent nested case-control epidemiological study of Europeans showed that elevated resistin concentration was not a predictor of ischemic stroke." (PMID 19922611, 2009). "Compared to non-diabetic subjects with low resistin, the age- and sex-adjusted OR of ischemic stroke was greater in non-diabetic subjects with high resistin (OR: 2.15; 95% CI: 1.13-4.10; p = 0.02), but not in diabetic subjects with low resistin (OR: 1.27; 95% CI: 0.35-4.62; p = 0.72)." (PMID 19922611, 2009).
non-alcoholic fatty liver disease (12 papers, 2014 to 2025). "We found for the first time an association between biopsy-proven nonalcoholic fatty liver disease and RETN −420C>G promoter polymorphism." (PMID 39045929, 2024). "In this genetic case–control association study, 150 biopsy-proven nonalcoholic fatty liver disease patients and 154 controls were enrolled and genotyped for the RETN rs1862513 (-420C>G) gene polymorphism using PCR–RFLP method." (PMID 39045929, 2024). "In humans, resistin is associated with severity of non-alcoholic fatty liver disease, fibrosis, cirrhosis and mitochondrial dysfunction in hepatocytes." (PMID 33142854, 2020). "Interestingly, the RETN −420C>G "C" allele was also associated with a decreased risk for nonalcoholic fatty liver disease too (p=0.042; OR=0.72, 95%CI=0.53–0.95)." (PMID 39045929, 2024). "Changes in miR-155 in obese mice can induce obesity and non-alcoholic fatty liver disease (NAFLD) and led to an increase in resistin, which regulates insulin sensitivity." (PMID 31207998, 2019). "As a result, resistin takes part in many situations that trigger inflammation, such as atherosclerosis and cardiovascular disease (CVD), non-alcoholic fatty liver disease (NAFLD), osteoporosis, cancer, Crohn’s disease, metabolic diseases, DM2 and autoimmune diseases." (PMID 39519480, 2024).
systemic lupus erythematosus (12 papers, 2008 to 2025). An autoimmune multi-organ disease typically associated with vasculopathy and autoantibody production. "Epidemiological studies have shown that the levels of serum adipokine such as leptin and resistin are associated with the risk of developing systemic lupus erythematosus (SLE)." (PMID 38805491, 2024). "Serum resistin has been correlated with proinflammatory cytokines, C‐reactive protein, total IgG and other inflammatory markers in systemic lupus erythematosus (SLE)." (PMID 40976999, 2025). "Studies have shown that resistin is present in an increased titer in lupus patients versus controls." (PMID 36293458, 2022). "Resistin has been examined concerning systemic lupus erythematosus (SLE), with a study correlating increased SLE disease activity scores and resistin levels to inflammatory markers in SLE." (PMID 40976999, 2025). "Additionally, resistin may act as a marker of inflammation in other rheumatic disorders such as systemic lupus erythematosus (SLE) and systemic sclerosis (SSc)." (PMID 29623147, 2018). "The aim of this study was to determine associations between serum levels of resistin and markers of inflammation and bone mineral density (BMD) in female patients with systemic lupus erythematosus (SLE)." (PMID 18234104, 2008).
coronary atherosclerosis (11 papers, 2012 to 2023). Atherosclerosis of the coronary vasculature. "Plasma resistin levels are positively associated with CRP and predictive of coronary atherosclerosis in humans." (PMID 28298189, 2017). "Resistin is a 12.5-kDa cysteine-rich adipokine that is constitutively secreted by adipose tissue; resistin levels in plasma correlate with inflammatory markers and coronary artery calcification, a measure of coronary atherosclerosis." (PMID 30406149, 2018). "The levels of resistin were compared to inflammatory markers and were prognostic of coronary atherosclerosis, independent of CRP." (PMID 34745775, 2021). "Plasma resistin levels were found to be correlated with markers of inflammation, such as IL-6 and TNF-α, and thus could predict coronary atherosclerosis in humans independent of CRP." (PMID 34209146, 2021).
dementia (11 papers, 2012 to 2025). Loss of intellectual abilities interfering with an individual's social and occupational functions. "In the case of resistin crude ORs showed significant association of increased levels of resistin with higher risk of all-cause dementia (OR = 2.50), MD (OR = 4.05) and VaD (OR = 3.02)." (PMID 28421328, 2017). "Interestingly, recent studies with AD patients described elevated levels of resistin compared to controls, suggesting a possible association between resistin levels and higher risks of dementia, however, these results are controversial." (PMID 37732123, 2023). "We have also replicated an earlier association of clinical “AD” with serum resistin levels and clarified that they may be related through the effect of depressive symptoms on dementia, most likely independently of AD-specific neurodegenerative changes." (PMID 31150419, 2019). "Recent reports have suggested a pro-inflammatory impact of resistin on the development of dementia, especially in vascular dementia in geriatric patients." (PMID 36978817, 2023). "In fact, several previous case-control studies have documented elevated resistin levels in neurodegenerative disorders such as dementia, Alzheimer’s disease and Multiple Sclerosis." (PMID 33651847, 2021). "Our approach has demonstrably selected for cases with significantly higher serum resistin levels relative to off-diagonal cases “protected” from a dementia diagnosis, i.e., by a GDS score ≤10." (PMID 31150419, 2019). "In the whole dementia group the mean levels of adiponectin (p = 0.002) and resistin (p = 0.00009) were significantly higher and leptin/adiponectin (L/A) ratio (p = 0.015) was significantly lower as compared to the control group." (PMID 28421328, 2017). "In comparison with the controls, significantly higher concentrations of adiponectin were stated in dementia of neurodegenerative origin (AD and MD), and significantly higher levels of resistin were observed in dementia with vascular changes (VaD and MD)." (PMID 28421328, 2017). "A very important observation concerns resistin which was stated to be a significant marker of inflammation in dementia especially in dementia of vascular mechanism." (PMID 28421328, 2017). "The relation of circulating resistin with dementia was studied by other authors but the results of studies that have since been published are inconclusive." (PMID 28421328, 2017). "The most interesting observation in our study is the presence of elevated levels of resistin in all patients with dementia, particularly in dementia with vascular changes in the brain (VaD and MD) in comparison with non-demented controls." (PMID 28421328, 2017). "We conclude that dementia of neurodegenerative origin is characterized by elevated adiponectin levels, whereas dementia with vascular changes by increase of resistin." (PMID 28421328, 2017). "Another interesting finding in our study is the significant positive correlation of resistin level with serum chitotriosidase activity stated in all patients with dementia, particularly in dementia with vascular changes." (PMID 28421328, 2017). "This study included participants with different types of dementia, and they were compared with controls with normal cognitive function.Adiponectin, leptin, resistin, pro-inflammatory markers, vitamin D, cholesterol, and markers of glucose metabolism were assessed." (PMID 37363537, 2023). "Association with inflammatory indicators may suggest the pro-inflammatory role of resistin in the development of dementia, especially in dementia of vascular mechanism." (PMID 28421328, 2017). "In logistic regression analysis crude ORs showed significant association of increased levels of resistin with higher risk of all-cause dementia, MD and VaD, however these associations were no longer statistically significant after controlling for the other risk factors." (PMID 28421328, 2017).
dementia (continued). "Highly significant positive correlation between the level of resistin and age and indices of inflammation (IL-6 and hsCRP, chitotriosidase activity) and a negative correlation with HDL-cholesterol and PON1 activity was stated in patients with all-cause dementia." (PMID 28421328, 2017). "In the present study, we did show a positive correlation of resistin with inflammatory indicators (interleukin-6 and CRP) and a negative correlation with anti-inflammatory markers (HDL-C and PON1 activity) in all dementia patients." (PMID 28421328, 2017). "On univariate analyses these included age, sex, CAD, dementia, ASA ≥ 3, smoking, eGFR, haemoglobin, 25(OH)D, PTH, leptin, adiponectin and resistin levels, but with different impact on specific outcomes by HF type." (PMID 22333003, 2012). "In the present study, in opposition to leptin and adiponectin (both in dementia and non-demented elderly controls) we did not observe any correlation between resistin and metabolic parameters i.e. BMI, fasting glucose, insulin and HOMA-IR index." (PMID 28421328, 2017). "Borderline negative correlation of resistin with MMSE score (indicating the severity of dementia) was observed." (PMID 28421328, 2017). "Moreover, we did not observe any correlation between resistin and adiponectin and leptin, both in whole dementia and control group (data not shown)." (PMID 28421328, 2017).
sarcopenia (11 papers, 2018 to 2025). Progressive decline in muscle mass due to aging which results in decreased functional capacity of muscles. "IL-1b measured within 48 hours of admission/surgery was positively associated with sarcopenia status at 7 days (β 0.24, CI 0.06 - 0.42), and resistin was negatively associated (β -0.12, CI -0.23 - -0.01)." (PMID 39012665, 2024). "Serum resistin levels were associated with systemic inflammation and can be used accurately and easily to predict sarcopenia in patients with COPD." (PMID 35903456, 2022). "In conclusion, serum resistin levels were shown to be associated with systemic inflammation and can be used accurately and easily to predict sarcopenia in patients with COPD." (PMID 35903456, 2022). "Additional prospective studies are needed to support the use of resistin levels as a predictor of risk for developing sarcopenia." (PMID 35903456, 2022). "Collectively, these results suggest that resistin may be associated with systemic inflammation and that serum resistin expression may serve as a biomarker for predicting sarcopenia in patients with COPD." (PMID 35903456, 2022). "As a secreted protein abundantly present in human circulation and readily quantifiable, resistin holds promise as a potential biomarker for various age-related conditions, including dementia, sarcopenia, and osteoporosis." (PMID 39983655, 2025). "Blood was drawn, and inflammatory biomarkers associated with Sarcopenia (IL-2, IL-4, IL-5, IL-6, IL-8, IL-10, TNF, adiponectin, leptin, resistin, BDNF, sTNFr-1 and sTNFr-2) was analysed." (PMID 37365209, 2023). "Another study involving 2,000 subjects based on abdominal CT images showed that abdominal muscle density was negatively correlated with resistin levels and that targeted exercise of abdominal muscles helped prevent the development of sarcopenia." (PMID 35903456, 2022). "The aim of this study was to assess the clinical value of circulating resistin in prospectively screening for sarcopenia in patients with COPD and to determine the cutoff value for use in clinical practice." (PMID 35903456, 2022). "The aim of this study was to determine the relationship between resistin levels and systemic inflammation and to assess the clinical value of circulating resistin for sarcopenia in patients with COPD." (PMID 35903456, 2022). "The AUC value for predicting sarcopenia based on resistin was 0.818 (95% CI: 0.711–0.926, p < 0.001)." (PMID 35903456, 2022). "Exercise studies have shown that 12 weeks of resistance training reduces plasma leptin and resistin levels, and concluded that long-term resistance training improves sarcopenia in people by reducing inflammatory markers and reducing adipose tissue." (PMID 35250869, 2022). "The sensitivity and specificity of the serum level of resistin for predicting sarcopenia were 93.02 and 62.16%, respectively [the cutoff point was 7.138 ng/ml, and the AUC value was 0.828 (95% CI: 0.753–0.903)]." (PMID 35903456, 2022). "Previous studies indicated that a systemic inflammatory factor (TNF-α) was associated with sarcopenia in patients with COPD, and resistin is involved in the activation of multiple inflammatory signaling pathways." (PMID 35903456, 2022). "Our results from the development and validation sets indicate that higher serum resistin levels (>7.138 ng/ml) have good predictive ability for sarcopenia." (PMID 35903456, 2022). "A previous study indicated that the mean resistin levels in patients with sarcopenia were 2-fold higher than those in healthy controls." (PMID 35903456, 2022). "This study was the first to clarify the predictive value of the serum resistin level for sarcopenia in patients with COPD." (PMID 35903456, 2022). "The predictive efficacy of the serum resistin level (AUC: 0.828) for sarcopenia was superior to that of the serum TNF-α level (AUC: 0.621)." (PMID 35903456, 2022).
sarcopenia (continued). "In this study, we demonstrated that the association of serum resistin levels with sarcopenia in patients with COPD was independent of age." (PMID 35903456, 2022). "This is the first study to identify resistin for predicting sarcopenia in patients with COPD." (PMID 35903456, 2022). "In addition, we determined the cutoff value of serum resistin level that distinguished sarcopenia and validated the cutoff value in an independent validation set." (PMID 35903456, 2022). "In this study, we identified TNF-α and resistin as predictors of sarcopenia in patients with COPD." (PMID 35903456, 2022). "Given the importance of adipose tissue M1 macrophage accumulation in ageing and obesity, adipose tissue secretion of resistin may be of significant consequence in sarcopenia." (PMID 30337633, 2018). "Increased inflammatory factors such as IL-6, resistin, TNF-α, and ROS production are also associated with NF-KB signaling and the ubiquitin-proteasome system in skeletal muscle, both of which may be involved in the pathogenesis of sarcopenia." (PMID 35250869, 2022). "Compared to individuals in the lowest resistin quartile (Q1), those in the highest quartile (Q4) were older, had slower gait speed, lower SPPB scores, and a higher prevalence of sarcopenia and polypharmacy (P = 0.002 to 0.049)." (PMID 39983655, 2025). "In contrast, newer myokines/adipokines FNDC5, METRNL, RETN, and NAMPT, together with AdipoQ in sarcopenia, were uniformly negatively correlated, suggesting a counter-regulatory or compensatory circuit activated by mitochondrial stress." (PMID 40869253, 2025). "Therefore, we next analyzed the relationship between resistin and TNF-α expression in patients with COPD and the predictive value of the resistin level for sarcopenia." (PMID 35903456, 2022). "The accuracy of circulating resistin levels in predicting sarcopenia in patients with COPD has not been established." (PMID 35903456, 2022). "The serum resistin levels in patients with sarcopenia were significantly higher than those in patients without sarcopenia." (PMID 35903456, 2022). "Whether resistin levels predict sarcopenia has not been established." (PMID 35903456, 2022). "The serum levels of resistin and TNF-α were significantly higher in patients with sarcopenia than in patients without sarcopenia." (PMID 35903456, 2022).